NOD2 (nucleotide binding oligomerization domain containing 2)
Diseases named in the same sentence as NOD2 in open-access papers (continued):
Sharing a sentence is not in itself a finding about the gene and the disease.
infection (continued). "The infection of murine EDMs with AIEC-LF82 showed higher bacterial load in ELMO1-KO, NOD2 KO EDMs, and ELMO1 KO EDMs treated with NOD2 inhibitors." (PMID 36694274, 2023). "In summary, during infection with Pm HN01 and Pm HN02, genes related to immune inflammation, such as Nod2 and Nlrc5, were generally upregulated and significantly activated the NOD-like receptor signaling pathway." (PMID 36838365, 2023). "NOD2 and RIPK2 were required for about half of the IFN-α and IFN-β transcription and secretion within 4 hours of infection with Mtb." (PMID 37262021, 2023). "Compared with the control group, S. Infantis elevated the expression of NOD1, NOD2, and RIP2 at 5 h post-infection." (PMID 36142312, 2022). "The results of this study suggest that NOD2 plays a key role in inducing both innate and adaptive immune responses that are required to control IVA infection." (PMID 36146565, 2022). "The phenotype of large necrotic foci was late, appearing in mice euthanized at 223, 275, 307 (Nod2-KO) and 254 (DKO) days post-infection, and only occurred in a minority of the animals." (PMID 35418999, 2022). "The ability of NOD1 and NOD2 to respond to ER stress further underscores the importance of NOD1 and NOD2 during infection control and the connection between ER stress and PRR responses to manage infections." (PMID 34748367, 2022). "Some of the transcripts related to infection by virus that were decreased include TRIM22, NOD2, IFITM3, and SPHK1." (PMID 36059515, 2022). "In regulating microbe-elicited ROS production during an antimicrobial response, many studies showed that host PRRs (mainly TLR2, TLR4, NOD2, NLRX1, and NLRP3) and redox modulation alleviated pathogen infection." (PMID 34299310, 2021). "This transcriptional upregulation is caused by other PRRs, such as Toll-like receptors (TLRs) and nucleotide-binding oligomerization domain-containing protein-2 (NOD2), at sites of infection." (PMID 33534121, 2021). "Common PRRs of NOD1, NOD2, NLRP3, NLRC4, NLRC5, and AIM2 were detected using qPCR assays after 90 min of infection with A. sobria at a MOI of 10 and 2 h gentamycin treatment followed by 12 h incubation." (PMID 34513725, 2021). "Impaired ATG16L1, IRGM or NOD2 expression in macrophages increases intracellular AIEC with enhanced secretion of IL-6 and TNF in response to infection." (PMID 33468624, 2021). "TNF constitutes one of the major pro-inflammatory cytokines produced following Nod2 activation and virus (RSV and IAV) infection." (PMID 34551004, 2021). "During infection, NOD1 and/or NOD2 represent an intracellular surveillance system inducing NF-κB activation by detecting cytoskeleton disruption, instead of monitoring RHO GTPases." (PMID 34201509, 2021). "In NOD2 overexpressing Caco-2 cells, AIEC infection led to a stronger increase in ATG16L1 protein expression associated with a decrease in AIEC survival and of pro-inflammatory cytokines release compared to WT Caco-2 cells." (PMID 32466328, 2020). "We would posit that the pleiotropic functions of Nod2 may be explained based on T cell-specific roles in antigen recognition vs. microbial sensing functions that help maintain balance between self-tolerance and host-defense mechanisms against infection, respectively." (PMID 33106495, 2020). "Similar levels of IL-17 and defensin-A mRNA expression was observed in NOD2-/- and C57BL/6 infected animals during acute phase of infection." (PMID 32986710, 2020). "Histopathological analysis of the colon and jejunum of NOD2-/- and wild type C57BL/6 animals revealed discrete inflammatory foci during the acute phase of infection." (PMID 32986710, 2020). "Meanwhile, the expression of NOD2, as well as inflammatory factors IL-1β, TNF-α, and IL-6 was markedly up-regulated in 24 h and 48 h after infection groups." (PMID 30186539, 2018). "Remarkably, we found that NOD2 mRNA expression was much greater in RIG-I KO mouse lung as compared with WT mice, especially at day 6 after infection." (PMID 30532653, 2018).
infection (continued). "In agreement with the role of Nod2 in antiviral response, Nod2KO and RIP2KO mice are hypersensitive to infection with RSV." (PMID 28253332, 2017). "Considering the importance of RIP2 in NOD2 signalling, understanding RIP2 regulation is critical for developing novel therapeutics to modulate NOD2 signalling during infection control and inflammatory conditions." (PMID 28656966, 2017). "Seven days following peroral infection with 109 CFU C. jejuni strain 81–176 on two consecutive days (i.e., days 0 and 1), however, Nod2 was down-regulated in the large intestines of both WT and IL-10−/− mice (p < 0.001 and p < 0.05, respectively)." (PMID 28752081, 2017). "Although a more detailed role of NOD2 in Th1 immunity should be investigated in the future, our data indicate that NOD2 may be involved in the control of M. abscessus growth during the late phase of infection by regulating T cell response and IFN-γ-mediated signaling." (PMID 29163541, 2017). "For example, different strains of S. aureus can activate different pattern recognition receptor (PRR) signaling cascades, specifically NOD2/IRF5 versus TLR9/IRF1, leading to different type I IFN responses that affect survival after infection." (PMID 27143388, 2016). "WT and NOD2-/- mice were infected with a lethal dose of IAV (3000 PFU) and daily treated (i.v.)with LTB4 (1 μg/kg) or placebo from day 1 to 10 post-infection." (PMID 26444420, 2015). "The local innate immune response of mammary glands was swiftly activated after S. aureus inoculation during the initial stage of infection, characterized by up-regulation of gene expression of TLR2, NOD2, TNF-α, IL-1β, IL-6, and CXCL1." (PMID 25990971, 2015). "In contrast to our findings related to NOD2, our data indicated that uninfected brain tissues express little or no NOD1, and only a modest level of expression was detectable following infection with the gram-positive bacteria S. pneumoniae." (PMID 25443778, 2014). "These authors observed, through the use of Nod1-/- and Nod2-/- mice, that IL-12 and TNF-α levels were reduced after infection." (PMID 24155744, 2013). "We infected TLR2-/- and Nod2-/- mice with lethal doses of IOE and compared the outcomes of infection to similarly infected wild type (WT) mice and naïve mice of both strains." (PMID 23526993, 2013). "Having observed that lethal IOE infection differentially modulates tlr2 and nod2 levels, we decided to elucidate the contributions of TLR2 and Nod2 to the pathogenesis of fatal ehrlichiosis." (PMID 23526993, 2013). "After intraperitoneal amastigotes inoculation in wild-type and knockout mice for TNF-α, Nod2, Myd88, iNOS, IL-12p40, IL-18, CD4, CD8 and IFN-γ we found that the latter is crucial for controlling infection by G strain amastigotes." (PMID 22509418, 2012). "In fact, for certain infections, impairment of NOD1 and NOD2 function interferes with both innate and adaptive immune responses." (PMID 23162548, 2012). "In this review, we will focus on functional aspects of the NOD1 and NOD2 proteins and discuss recent findings related to their roles in microbial recognition and the induction of inflammatory responses that lead to the restriction of infections with bacterial and non-bacterial pathogenic microbes." (PMID 23162548, 2012). "Nonetheless, increased NOD2 levels, which correlate with TLR2 and TLR4 expression, were noted in some patients with severe infection." (PMID 17705850, 2007). "In human hepatocytes, NOD1 expression significantly increases following infection; however, NOD2 levels are not significantly impacted." (PMID 39878363, 2025). "Mouse‐ or human‐derived cells prestimulated with BCG displayed NOD2‐induced trained immunity, showing nonspecific protection against infection and increased pro‐inflammatory cytokines IFN‐γ, TNF‐α, and IL‐1β." (PMID 41017210, 2025). "In addition, all seven experimental groups were compared to the control group in terms of genes related to infection and inflammation, such as NOD1 and NOD2." (PMID 39474054, 2024).
infection (continued). "Autophagy plays a protective role in the gut epithelium, and certain innate immune mechanisms are only evident during infection of the gut epithelium, exemplified by NOD2-mediated restriction of Lm growth during oral but not intravenous infection." (PMID 37352334, 2023). "Case reports have been published identifying NOD2 mutations in patients with M. abscessus or MAC infection, but controlled genetic studies associating NOD2 with these infections have not been performed." (PMID 37262021, 2023). "NOD2 is a pattern recognition receptor (PRR) that plays a key role in the presence and magnitude of the immune and inflammatory responses, thus determining infection outcome." (PMID 36877680, 2023). "At 6 weeks post-infection, DKO mouse lungs were more congested than WT controls and but without lymphocytic clusters, consistent with what has been demonstrated before with Nod2-KO mice." (PMID 35418999, 2022). "Notably, NOD1 and NOD2 have been detected in the plasma membrane at the infection sites and upon activation by peptidoglycans both NOD1 and NOD2 induce the phosphorylation of their common adaptor receptor-interacting protein kinase 2 (RIP2)." (PMID 35846362, 2022). "Several studies have revealed that in the absence of NOD2, a strong antiviral response does not occur and the control of infection and viral replication is impaired." (PMID 36146565, 2022). "Thus, it is increasingly clear that infection responses mediated by NOD1 and/or NOD2 to promote inflammation is critical to control enteric infections, such as C. rodentium." (PMID 34748367, 2022). "Other factors, such as activation of inflammatory signaling, dietary changes, infection, and lack of nucleotide-binding oligomerization domain 2 (NOD2), can also lead to dysbiosis." (PMID 33494784, 2021). "Mice lacking both NOD1/NOD2 or RIP2, an adaptor protein of NOD1/NOD2, exhibited higher bacterial burdens after infection with Chlamydia and an NOD1/2-dependent TUDCA-sensitive inflammatory response." (PMID 32487756, 2020). "Compared to synthetic ligands iE-DAP and MDP, E. faecium with a multiplicity of infection (MOI = 1) activated NOD2, but not NOD1." (PMID 30969170, 2019). "Our data suggested that NOD2 activity began to increase in brain tissue 12 h after infection, while those of IL-1β, TNF-α, and IL-6 showed no obvious changes at 12 h." (PMID 30186539, 2018). "Histopathological analysis of the mouse lungs prior to infection did not reveal any significant difference between wild type and Nod2−/− mice." (PMID 29234083, 2017). "Nod2 regulates the bacterial clearance by controlling the production of CCL2 and the subsequent influx of circulating inflammatory monocytes at the site of infection." (PMID 28253332, 2017). "Again, only the “High Nod2-stimulating,” and not the “Low Nod2-stimulating” consortium rescued defects in infection-induced GM-CSF production in antibiotic-treated mice." (PMID 29142211, 2017). "Similar to non-transduced cells, MDP treatment after infection further induced NOD2, IFN-β and IL8 mRNAs in control (GIPZ) infected cells." (PMID 26830977, 2016). "Together, these data suggest that Nod2-triggered responses are required, although not essential, for N. caninum growth restriction during in vivo infection." (PMID 27377650, 2016). "During infections with the protozoan parasite Trypanosoma cruzi, studies indicated that NOD2 is not required for host protection." (PMID 28004792, 2016). "We observed that the absence of functional Nod2 did not alter the absolute number of peritoneal exudates cells after 5 days of infection (data not shown), as well as the proportion of macrophages (CD11b+ cells), neutrophils (Ly6G+ cells) and CD4+ cells." (PMID 27377650, 2016). "Similarly, infection of murine macrophages with murine norovirus-1 (MNV1) induced NOD1 and NOD2 in an IFN-β-dependent manner, and subsequent bacterial infection enhanced activation of NOD1/2, mediated by type I IFNs34." (PMID 26830977, 2016).
infection (continued). "The gene products of NOD1 and NOD2 are key cellular receptors that recognize intracellular pathogens and have been shown to be important in the recognition of MAP in epithelial cells early in infection." (PMID 27093613, 2016). "Although the absence of functional Nod2 did not compromise the survival and parasite clearance at the initial site of the infection, Nod2−/− mice presented a four-fold higher parasite load in the pancreas, if compared to infected WT littermates." (PMID 27377650, 2016). "Infection with all three viruses (Towne, TB40 and a clinical isolate) resulted in robust induction of NOD2 transcripts at 12 and 72 hours post infection (hpi), while in non-infected HFFs NOD2 mRNA was undetectable." (PMID 24671169, 2014). "The pulldown of Erbin with NOD2 is enhanced during infection; however, NOD2 is not dependent on Erbin for membrane localization." (PMID 25520185, 2014). "At two days post-infection (p.i.), colonization of the intestine and systemic organs (not shown) of C57Bl/6 and Nod2−/− mice was similar for both wild-type and ΔmsbB S. Typhimurium." (PMID 25423082, 2014). "Certain instances result in upregulation of Nod2 in the presence of Plasmodium sporozoites, while in other cases Nod1 and Nod2 confer changes in cytokines but do not promote survival after infection." (PMID 24155744, 2013). "Recently, Vissers and coworkers stimulated human PBMCs with RSV and the common bacterial ligand MDP, and showed that primary infection with RSV induces IFN-β, which leads to the upregulation of NOD2 and subsequent signaling of NOD2 by MDP then induces a higher proinflammatory cytokine response." (PMID 24244872, 2013). "In contrast, the lack of TLR2 and unrestricted function of Nods in TLR2-/- mice could lead to uncontrolled IOE infection and immunopathology, which is consistent with the phenotype of IOE-infected Nod2-/- mice." (PMID 23526993, 2013). "Both synthetic ssRNA and ssRNA viral genomes activated IRF-3 in a NOD2- and MAVS-dependent manner, and infection with RSV resulted in increased NOD2 expression, leading to IFN production within 2 h p.i., whereas other PRRs (e.g., RIG-I) activate the IRF-3-IFN pathway during a later infection period." (PMID 24244872, 2013). "Regardless of the roles of NOD1 and NOD2 in the immune response to certain microbes, for some bacterial pathogens, such as Coxiella burnetii and Brucella abortus, NOD1 and NOD2 play no role in restricting bacterial replication in murine models of infection." (PMID 23162548, 2012). "Previous studies have shown that cells that undergo prolonged stimulation of Nod2, mimicking prolonged infection, no longer respond to subsequent stimulation by bacterial ligands, such as LPS, thus becoming tolerant to those stimuli." (PMID 21387014, 2011). "In order to assess the importance of Nod2 and Rip2 to the downstream IFNα/β-dependent macrophage response, we quantified the induction of RANTES mRNA, which depends on type I IFN secretion and signaling via the IFNαβ receptor (IFNAR1) in this infection model." (PMID 19578435, 2009). "Similar observations were made for NOD2, not only with corneal epithelial cells, but also in A549 lung epithelial cells, THP-1 monocyte, and RAW264 macrophage cell lines, where infection with A. fumigatus conidia led to increased expression of NOD2 and cytokine release." (PMID 41249509, 2025). "Furthermore, experimental models of Crohn’s disease show that infection with enteric parasites confers protection in mice from intestinal abnormalities due to the lack of Nod2 gene during infection with bacterioides species." (PMID 41236793, 2025). "We observed using confocal microscopy and co-immunoprecipitation assays that NOD2 interacts with the effector protein MAVS (mitochondrial antiviral signaling protein), an adaptor protein promoting antiviral activity, this occurring mainly at 12 h into the infection." (PMID 38668261, 2024).
infection (continued). "However, after infection with Pm HN01 and Pm HN02, the expression of Nod2 was significantly upregulated, which may be attributed to the PGN fragment in the P. multocida periplasmic space." (PMID 36838365, 2023). "Notably, the NOD-like receptor proteins NOD1 and NOD2 can participate in innate immune responses, and NOD1 stimulates the release of chemokines, such as CXCL-8, CXCL-1, and CXCL-2, which can attract neutrophils to the site of infection." (PMID 35993024, 2022). "Once internalized, mycobacterial specific N-glycolyl MDP is recognized and activates NOD2, leading to synergistic interactions with TLRs and TLR heterodimers (TLR2, TLR1, and TLR6) to promote downstream activation of NF-κB signaling and a pro-inflammatory response to infection." (PMID 34485444, 2021). "Considering that infection by IOE and E. muris produce distinct in-vivo phenotypes (fatal vs. mild disease, respectively), recognition by Ehrlichia involving TLR2 or NOD2 signaling in macrophages could be hypothetically correlated with the particular polarization into M1 or M2 types." (PMID 31575880, 2019). "Importantly, only the “High Nod2-stimulating,” and not the “Low Nod2-stimulating” consortium rescued defects in infection-induced GM-CSF production in antibiotic-treated mice." (PMID 29142211, 2017). "Additionally, our results suggest that pathogenesis induced by Nod2 after lethal infection protocols with N. caninum is independent of the canonical signaling pathway for this receptor." (PMID 27377650, 2016). "The role of NOD2 during parasite infections has not been studied as extensively." (PMID 28004792, 2016). "NOD2 was again undetectable in non-infected HFFs, but was not induced after infection with HSV1." (PMID 24671169, 2014). "Infection with human herpesvirus 1 and 2 does not induce NOD2 expression." (PMID 24671169, 2014). "However, lethal infection induced higher expression of nod2 on day 7 p.i. compared to nonlethal infection." (PMID 23526993, 2013). "This suggests that Nod2 does not play a major role in reducing bacterial burden and may, in fact, hinder control of infection." (PMID 21387014, 2011). "Several Nod-like receptor (NLR) family genes (nucleotide-binding oligomerization domain (NOD) 1, NOD2, NLRP2, NLRP3 and class II trans-activator (CIITA)) which act as intracellular sensors to detect cytosolic microbial components and "danger" signals were elevated upon infection." (PMID 21110886, 2010). "Thus, the mammalian Nod2 pathway appears to be remarkably sensitive to mycobacterial MDP and responds to infection by triggering the production of type I interferon, which is responsible for a significant component of the transcriptional response to Mtb infection." (PMID 19578435, 2009). "In addition, NOD1 and NOD2 may be activated by PGN fragments, introduced into host cells during infection by pathogens that possess auxiliary secretion systems." (PMID 17397264, 2007). "In addition to the activation of each of the PRRs, the multiple signaling pathways of NOD1, NOD2, and TLR act synergistically in stimulating intracellular signaling cascades to produce more pro‐inflammatory factors, which are involved in the early innate immune response to infection." (PMID 41017210, 2025). "Given that many pathogens induce ER stress and that peptidoglycan-free viruses and parasites activate NOD1 and/or NOD2-dependent inflammation, it is reasonable to speculate that NOD1 and/or NOD2 are activated by sensing the ER stress and possibly SAMPs during these infections." (PMID 34201509, 2021). "Given that Nod2−/− mice showed increased resistance to infection, despite the lack of adequate control of parasite loads in determined tissues, we speculated if these phenomena could be associated with a reduction of tissue damage due to a milder inflammatory response." (PMID 27377650, 2016).